AKT1 (AKT serine/threonine kinase 1)
Diseases named in the same sentence as AKT1 in open-access papers (continued):
Sharing a sentence is not in itself a finding about the gene and the disease.
melanoma (continued). "In melanoma patients, macrophages that are co-localized with AKT1 are correlated with disease aggressiveness, and immunotherapy non-responders are enriched in macrophages containing melanosome markers." (PMID 38719996, 2024). "Dysregulation of the PI3K-AKT pathway in melanomas is commonly observed through mutations or amplifications in genes such as PTEN, PIK3CA, and AKT1." (PMID 38247727, 2024). "We elucidate that AKT2 is dispensable for primary tumor formation but promotes migration and invasion in vitro and metastatic seeding in vivo, whereas AKT1 is uniquely important for melanoma initiation and cell proliferation." (PMID 37894325, 2023). "This study suggests that specifically targeting AKT2 and AKT1 represents novel therapeutic strategies for different-stage melanoma patients." (PMID 37894325, 2023). "SPI1 knockdown restrained melanoma cell proliferation, metastasis and glycolysis by regulating the AKT1/mTOR pathway." (PMID 37539493, 2023). "The p‐AKT1, AKT1, p‐mTOR and mTOR protein levels in melanoma tissues were detected by immunohistochemistry assay, indicating that p‐AKT1 and p‐mTOR proteins were significantly increased in melanoma tissues." (PMID 37539493, 2023). "Herein, we verified that SPI1 regulated HK2 expression, thereby mediating the AKT1/mTOR signalling pathway and promoting melanoma cell proliferation, metastasis and glycolysis." (PMID 37539493, 2023). "Our data support an isoform-specific role for AKT2 in melanoma metastasis, with a shared role for AKT1 and AKT2 in tumorigenesis." (PMID 37894325, 2023). "Altogether, our work elucidated that downregulation of SPI1 hampered cell proliferation, metastasis and glycolysis in melanoma cells by blocking the AKT1/mTOR axis by targeting HK2." (PMID 37539493, 2023). "We further show that while AKT2 is dispensable for melanoma initiation, AKT1 contributes to BRAF-driven murine melanoma initiation and cell proliferation, which is in line with our previous results." (PMID 37894325, 2023). "A network reconstructed from the selected functions shows a strong integration with the functions involved in colon cancer and melanoma, namely AKT1, EGFR and MAPK3." (PMID 37629086, 2023). "The serine–threonine kinase 1 (AKT1)/mammalian target of rapamycin (mTOR) axis is involved in melanoma progression." (PMID 37539493, 2023). "We found that AKT2 specifically regulates melanoma cell metastasis through effects on metabolism and melanoma cell properties, while AKT1 is involved in cellular proliferation and growth." (PMID 37894325, 2023). "This suggests that AKT1 promotes melanoma initiation and growth, which is consistent with a well-described role for AKT1 in tumor promotion and cell proliferation and survival." (PMID 37894325, 2023). "Despite the apparent inability of AKT1 to fully support metastasis in AKT2-depleted human melanoma cells, hyperactive AKT1 contributes to the metastatic potential of the mouse SM1-750 model." (PMID 37894325, 2023). "In another study, luteolin suppressed melanoma cell proliferation and induced apoptosis via the inhibition of phosphorylation of AKT1 and PI3K, two pathways involved in the control of cell growth and survival." (PMID 37687080, 2023). "Here, we show for the first time an essential, isoform-specific role for AKT1 in senescence induction in melanoma cells by Palbociclib." (PMID 35158840, 2022). "It has been demonstrated that the activation of AKT1 results in the development of more metastatic melanomas in mice." (PMID 35883768, 2022). "In melanoma, AKT1 and AKT2 activation are more commonly found in BRAF-mutant tumors, while AKT3 hyperactivity is more common in BRAF wild-type melanomas." (PMID 35158840, 2022). "Here, we show for the first time an AKT1 isoform-specific role in cellular senescence induced by CDK4/6 inhibition in human melanoma cell lines." (PMID 35158840, 2022).
melanoma (continued). "Using isoform-specific guide RNAs (gRNAs), we used CRISPR-Cas9 to knockout AKT1, AKT2, or AKT3 in multiple melanoma cell lines, validating the success of AKT knockout by Western blotting." (PMID 35158840, 2022). "Downstream effectors of AKT1, such as the mTORC1 protein, have key effects on the metabolism of melanoma cells." (PMID 34831420, 2021). "For instance, miR-637 suppresses the proliferation and invasion of hepatoma cells by down-regulating AKT1 and inhibits melanoma progression through PTEN/AKT signaling pathway." (PMID 33659023, 2021). "In terms of oxidative stress, a study that transfected active AKT1 into WM35 melanoma cells produced an increase in reactive oxygen, particularly superoxide." (PMID 34831420, 2021). "Taken together, NVD-BM was identified as a tumor suppressor in malignant melanoma, and we established a dual-input biosensor to promote cancer cell regression, via Akt1/NF-κB signaling." (PMID 32712598, 2020). "Together with downstream target protein mTOR, the activated AKT1 induces highly metastatic melanomas involving lung (67%) and brain (17%) in BRAFV600E/Cdkn2aNull mice." (PMID 32962182, 2020). "In melanoma brain metastasis, AKT1 and AKT3 are sites of mutation and the expression of AKTe17k seems to be connected with the higher probability of melanoma brain metastases (MBMs) and shorter survival in the murine model." (PMID 32575838, 2020). "Another essential factor constitutively active in melanoma is the serine/threonine kinase Akt1, which is an oncogene leading to tumor progression and also known as an IKKε target." (PMID 32630674, 2020). "Here, oncogenic RAS variants, and constitutively active MEK1 or AKT1, caused nuclear localization of myc-tagged GLI1 in the human melanoma cell line SK-Mel2." (PMID 33081032, 2020). "We have uncovered a potential role for the regulatory network motif UCA1/AKT1/hsa-miR-125b-1 in melanoma." (PMID 32703153, 2020). "To determine the effect of Akt1 on tumor angiogenesis, we subcutaneously injected melanoma cells into wild‐type littermates and into Akt1 knockout mice." (PMID 30984553, 2019). "As an example, we visualized a gene count plot for AKT1 (V-Akt murine thymoma viral oncogene homolog 1), as this gene overlapped between both sets of genes ranked by centrality and has a known role in melanoma tumorigenesis." (PMID 30820351, 2019). "As both mucosal and metastatic cutaneous melanomas showed high frequency of p-Akt1 expression, our findings suggest that mucosal melanomas have a biological behaviour that is similar to the one identified in aggressive cutaneous melanomas." (PMID 30647870, 2018). "In fact, several studies have addressed the role of p-Akt1 in cancer progression and metastasis, including its important part in the development of melanoma metastases in a mice model." (PMID 30647870, 2018). "Multivariate analysis showed p-Akt1 to be an independent prognostic marker in oral (P = .041) and sinonasal (P < .0001) melanomas patients." (PMID 30647870, 2018). "As both mucosal and metastatic cutaneous melanomas showed high frequency of p-Akt1 expression, these findings suggest that mucosal melanomas have a biological behaviour, similar to the aggressive cutaneous melanomas." (PMID 30647870, 2018). "The sinonasal melanomas demonstrated a higher number of nuclei positive for p-Akt1 (mean = 56.15%, ranging from 15.1% to 82.6%), statistically different from the other subtypes of melanomas analysed in this cohort." (PMID 30647870, 2018). "In the context of melanoma, an overgrowing interest in determining as p-Akt1 acts during melanoma progression has been recently observed, and its inhibition has emerged as an interesting targeted therapy for these tumours." (PMID 30647870, 2018). "Other mutations observed in MAPK signalling intermediates in melanoma cells include MEK1 (C121S and P124L), MEK2 (Q60P and C125S) and AKT1 (E17K)." (PMID 28708099, 2017).
melanoma (continued). "CHER selection of AKT1 and PTEN suggests the PI3K/AKT pathway is predictive of resistance to paclitaxel in melanoma cells." (PMID 26274927, 2015). "Of the three AKT family members (AKT1–3), about 50% of melanoma cells have constitutive activity in AKT3." (PMID 19156138, 2009). "Furthermore, the same study used human melanoma specimens and positively correlated macrophages histologically co-localized with AKT1 with more progressive disease." (PMID 39866233, 2025). "Over the past few decades, research has primarily focused on defining the genomic landscape of primary melanoma and metastatic disease, uncovering key genetic alterations, such as BRAF, NRAS, AKT1, and PTEN mutations, that shed light on melanoma progression and treatment resistance [3,4,]." (PMID 40669378, 2025). "Interestingly, a recent study has shown that the precursor to vitamin D3, 7DHC, can suppress melanoma cell proliferation and invasion via inhibition of AKT1/NFκB signaling." (PMID 38927967, 2024). "Another study on melanoma found that luteolin affected the phosphorylation of AKT1 and PI3K." (PMID 38474604, 2024). "We previously showed that melanoma cell-derived melanosomes transform dermal fibroblasts into CAFs, and therefore we examined whether AKT1 is a CAF-related protein." (PMID 38719996, 2024). "We observed that AKT1 loss extended overall survival in melanoma-prone mice, while AKT2 and AKT3 loss did not." (PMID 37894325, 2023). "As a potential mechanism of acquired resistance, it has been reported that mutation-specific ctDNA assays allow early detection of the onset of NRAS mutation in patients treated with BRAFi, other than mutations in MAP2K1, AKT1, and PIK3CA in melanoma patients showing treatment resistance." (PMID 37627054, 2023). "Our approach supports the role of AKT1 and MDM2 protein signatures as drivers of EMT in melanoma cancer and suggests that MDM2 plus AKT1 inhibitors could be a promising combination for a novel anti-metastatic regimen in high E2F1-expressing melanoma patients." (PMID 37993971, 2023). "In this study, p‐AKT1 and p‐mTOR levels were dramatically elevated in melanoma tissues, indicating that the AKT/mTOR signalling pathway might be involved in regulating melanoma progression." (PMID 37539493, 2023). "Importantly, AKT signaling has been connected to senescence, and specifically AKT1 isoform-specific inhibition has been suggested as a novel therapeutic target in melanoma." (PMID 37993971, 2023). "By contrast, even though mutations in the catalytic subunit of PI3K, or AKT1, AKT2, and AKT3, are rare in melanoma, immunopositivity of AKT3 is common in melanoma, and could activate PI3K–AKT–mTOR in PTEN wild type tumors." (PMID 36135270, 2022). "However, given the link of large oncosomes to cell metabolism and EGFR/AKT1 pathways, their role in melanoma merits further exploration." (PMID 35804857, 2022). "Other studies demonstrate that Akt1 activation promotes melanoma metastasis." (PMID 34419139, 2021). "Notably, AKT1 activation is sufficient to transform noninvasive melanoma into an invasive form in vivo." (PMID 34831420, 2021). "The lncRNAs that have been associated with melanoma metastasis and their corresponding microRNA and upregulated transcripts include KCNQ1OT1/miR-153/MET, LINC00518/miR-204-5p/AP1S2, LINC00520/miR-125b-5p/EIF5A2, and UCA1/hsa-miR-125b-1/AKT1." (PMID 35008286, 2021). "When excluding AKT1-mutated patients and considering only NF1 mutations with more deleterious effects (nonsense, frameshift, and splicing variants), the most frequent cancer types are non-small cell lung cancer (12%), glioma (10%), and melanoma (9%)." (PMID 32858845, 2020). "Furthermore, the BRAF alteration is often associated with mutations of PTEN, an inhibitor of the PI3 kinase/Akt1 pathways, which in turn causes an increased activation of PI3K/Akt1 and can further enhance melanoma progression." (PMID 32630674, 2020).
melanoma (continued). "Furthermore, to specifically deplete macrophages and microglia, we treated AKT1-expressing larvae with the CSF-1R inhibitor Ki20227 that has previously been shown to deplete macrophages and to reduce tumor growth in a rodent melanoma model." (PMID 29465400, 2018). "In one of them, analysis of 100 biopsies from relapsed melanoma identified MAPK alterations in 70% of patients, and 22% had acquired alterations in PI3K pathway, including a novel mutation in the pleckstrin homology domain of AKT1." (PMID 24743024, 2014). "Interestingly, the level of phosphorylated Akt1 is very low in the studied melanoma cell lines." (PMID 39195238, 2024). "Moreover, it has been shown that AKT1 promotes melanoma brain metastasis." (PMID 36339598, 2022). "Moreover, both AKT1 and AKT2 have been implicated in melanoma metastasis." (PMID 35158840, 2022). "Furthermore, the aberrant regulation of AKT1 is also prevalent, found in 43–67% of melanomas." (PMID 34831420, 2021). "In A375 human malignant melanoma cells, arbutin at high concentration (1 mM) up-regulated 88 genes and down-regulated 236 genes, including genes (AKT1, CLECSF7, FGFR3, and LRP6) controlling cell cycle progression, hence, suggesting that it may act similarly on neutrophils." (PMID 32731392, 2020). "It was shown to be downregulated and might function as a tumor suppressor by targeting Myc, FSCN1 in gastric cancer, ZEB1 in oral squamous cell carcinoma, CRKL in hepatocellular carcinoma, TLN1 in nasopharyngeal carcinoma, AKT1 in melanoma, or BCL2 and SP1 in esophageal carcinomas." (PMID 33414893, 2020). "Therefore, particularly in mucosal melanomas, a correlation between p-Akt1 overexpression and c-KIT mutation may help to understand how these pathways are important for melanoma pathogenesis and patient outcomes." (PMID 30647870, 2018). "To investigate the impact of the treatments on key signaling pathways involved in melanoma progression, we evaluated the expression and activation status of ERBB2, BRAF, PI3K, AKT1, and mTOR by immunofluorescence analysis." (PMID 40806647, 2025). "Both compounds exhibited favorable binding energies with several targets, including PI3K, AKT1, mTOR, BRAF, and ERBB2, all of which are critical regulators of cell proliferation and survival in melanoma." (PMID 40806647, 2025). "We investigated the expression profiles of AKT1 and MDM2 and their impact on melanoma patient survival using the Kaplan-Meier curve using the TCGA melanoma SKCM dataset." (PMID 37993971, 2023). "In PTEN null melanomas and in the human cell lines in our study, a key difference is significant AKT1 phosphorylation, which could compensate to drive tumor cell growth and survival, given the cellular sensitivity to AKT1 depletion in cell proliferation and tumor growth that we observed." (PMID 37894325, 2023). "With the computational pipeline used in this study, we were successful in the identification of key protein signatures (AKT1 and MDM2) in melanoma from a core regulatory network that is based on a published E2F1 interaction map." (PMID 37993971, 2023). "Our model simulations identified two protein signatures AKT1 and MDM2 as potential drivers of EMT in melanoma." (PMID 37993971, 2023). "In general, our work indicated that the transcription factor SPI1 promoted melanoma cell proliferation, metastasis and glycolysis by promoting HK2 expression and activating the AKT1/mTOR signalling pathway." (PMID 37539493, 2023). "This is in line with our data showing only strong AKT1 phosphorylation in primary mouse tumors, distinguishing the role of AKT2 in metastatic seeding from the role of AKT1 in primary murine melanoma formation." (PMID 37894325, 2023).
melanoma (continued). "Tumor angiogenesis was examined by subcutaneously injecting B16BL6 melanomas into Akt1∆SMC and Akt2∆SMC mice to further determine the role of Akt1 in VSMCs." (PMID 35931736, 2022). "Alterations in other important constituents of the PI3K/AKT pathway, namely RAC1, PIK3CA, AKT3, PREX2, and AKT1, are also known to occur in melanoma." (PMID 35008286, 2021). "Collectively, these data indicated that NVD-BM promoted tumor regression by decreasing phosphorylated Akt1 levels, and inhibiting free RELA translocation into the nucleus in melanoma cells." (PMID 32712598, 2020). "In this study, differential expression analyses revealed that many genes, including AKT1 and CDK2, play important roles in melanoma." (PMID 30385854, 2019). "Some of these DEGs had been investigated previously, including CDK2, AKT1 and KIT, which have been widely accepted as oncogenes in melanoma." (PMID 30385854, 2019). "Although the effects of PIPP loss on melanoma cell migration and metastasis have not been reported, it is interesting to speculate that this may lead to increased cell migration and metastasis via AKT1 activation." (PMID 28082369, 2017). "One of the key effector proteins in this pathway is known as PKB (protein kinase B) or AKT, which has three isoforms (AKT1, AKT2, and AKT3), with AKT3 being found frequently activated in melanomas." (PMID 28430130, 2017). "Treatment of melanoma cells with AKT1 inhibitors decreased the number of cells with nuclear Gli1 labeling, while increasing the number of cells with cytoplasmic Gli1 labeling, suggesting that AKT1 may be required for Gli1 nuclear localization and transcriptional activity." (PMID 26512695, 2015). "In melanoma cells, oncogenic Ras activity, dominant active MEK1 and dominant active AKT1 all increased the subcellular nuclear localization of exogenous Gli1." (PMID 26512695, 2015). "The process involves AKT1 transfer from melanosomes to macrophages, activating mTOR phosphorylation and triggering excessive VEGF secretion, which elevates proliferation rates in melanoma cells." (PMID 41417432, 2025). "Inverse to the impact of exogenous ARSB and pertinent to the development of melanoma, ARSB silencing increased CHST15 expression, abundance of C4,6S disaccharides, and activation of phospho(Tyr)-ROR1 and phospho(Ser473)-AKT1 and reduced nuclear FOXO3a and COP1 expression." (PMID 40562100, 2025). "Given the lack of efficacy of AKT inhibitors in melanoma, we used our established mouse models to further elucidate the molecular mechanisms by which AKT1 contributes to metastatic spread in an effort to identify alternative therapeutic targets." (PMID 39922199, 2025). "Fibroblast-derived melanosomes contained AKT1, not present in melanosomes that originated from melanoma cells." (PMID 38719996, 2024). "Indeed, TBX3 has been shown to be regulated by AKT3 and AKT1 (key mediators of PI3K signalling) through posttranslational phosphorylation resulting in stabilisation and nuclear localisation in melanoma and fibrosarcoma cells respectively." (PMID 39403898, 2024). "Expression of BRAFV600E in Cdkn2aNull mice generates melanomas without metastasis, but AKT1 activation promotes development of CNS metastases in this model." (PMID 37920169, 2023). "By using a conventional in vitro wound healing assay, it was found that only AKT2 depletion and not AKT1 or AKT3 depletion inhibited cell migration in three different human melanoma cell lines." (PMID 37894325, 2023). "Recently, in CD271+ melanoma cells, Akt3 (unlike Akt1 and Akt2) was identified as the most expressed protein sustaining cell survival." (PMID 37189846, 2023).